CERNA2 (competing endogenous lncRNA 2 for microRNA let-7b)
Synonyms: HOST2; lncRNA-HOST2
Gene: Long non-coding RNA gene on chromosome 10 (84,167,228 to 84,172,094, reverse strand). Ensembl gene ENSG00000285972.
Diseases named in the same sentence as CERNA2 in open-access papers:
CERNA2 is named in the same sentence as 17 diseases in open-access papers, as found by Europe PMC text mining. Sharing a sentence is not in itself a finding about the gene and the disease. The quoted sentences say what the papers report.
ovarian carcinoma (11 papers, 2016 to 2022). A malignant neoplasm originating from the surface ovarian epithelium. "CERNA2/HOST2 was shown to promote ovarian cancer cell proliferation, partly by sponging the tumor suppressor let-7b." (PMID 34681900, 2021).
psoriasis (2 papers, 2021 to 2023). An autoimmune condition characterized by red, well-delineated plaques with silvery scales that are usually on the extensor surfaces and scalp. "Only LINC01215, LINC1206, LINC1269, SH3PXD2A-AS1, CERNA2 and PRKCQ-AS1 have known functions and pathways associated with psoriasis pathogenesis." (PMID 38003532, 2023). "We also corroborated the involvement of eight lncRNA genes involved in psoriasis as determined by previous studies, including EPHA1-AS1, CYP4Z2P, SNHG12, LINC01215, LINC1206, SH3PXD2A-AS1 and CERNA2." (PMID 38003532, 2023). "Particularly, PRKCQ‐AS1, SH3PXD2A‐AS1 and CERNA2 are positively correlated to STAT1, indicating that the up‐regulated lncRNAs may participate in the progression of psoriasis through fine‐tuning the regulation of IFN‐γ signalling pathway." (PMID 34080300, 2021).
cervical cancer (1 paper, 2022). A primary or metastatic malignant neoplasm involving the cervix. "Additionally, CERNA2 was up-regulated in HPV-positive cervical cancer cells, resulting in the down-regulation of its target microRNA let-7b." (PMID 36458289, 2022).
cancer (5 papers, 2017 to 2025). A tumor composed of atypical neoplastic, often pleomorphic cells that invade other tissues. "It is notable that the expression of CERNA2 has been shown to correlate with poor clinical parameters and an unfavourable prognosis of different cancer patient groups while silencing of CERNA2 expression inhibits cancer cell growth and promotes cell apoptosis." (PMID 38514698, 2024).
CERNA2 also shares sentences with these, for which no sentence is quoted: tumor (6 papers); gastric cancer (2); glioma (2); hepatocellular carcinoma (2); breast carcinoma (1); Depression (1); lung carcinoma (1); lymph node metastasis (1); osteosarcoma (1); pancreatic cancer (1); prostate carcinoma (1); renal cell carcinoma (1); triple-negative breast carcinoma (1).